MYCN (MYCN proto-oncogene, bHLH transcription factor)
Diseases named in the same sentence as MYCN in open-access papers (continued):
Sharing a sentence is not in itself a finding about the gene and the disease.
neuroblastoma (continued). "Reduction of MYCNOS-01 or MYCN expression decreased cell growth in MYCN-amplified alveolar rhabdomyosarcoma and neuroblastoma cell lines." (PMID 29466962, 2018). "Previous studies have used murine neural crest systems to investigate neuroblastoma development by MYCN transformation of primary neural crest cells derived from day 9.5 mouse embryos." (PMID 30515222, 2018). "To analyze the effects of MYCMI-6 on tumor physiopathology in vivo, we utilized a mouse xenograft tumor model based on human MYCN-amplified SK-N-DZ neuroblastoma cells." (PMID 29968736, 2018). "Despite the identification of MYCN amplification as an adverse prognostic marker in neuroblastoma, MYCN inhibitors have yet to be developed." (PMID 29880876, 2018). "MYCN-amplified neuroblastoma has a worse response to therapy and higher rate of both de novo drug resistance, treatment associated drug resistance, and recurrence compared to MYCN non-amplified tumors." (PMID 29755654, 2018). "Correlating the functional shRNA screen results with analysis of master regulators of MYCN amplification neuroblastoma allowed us to overcome the limitations of in vitro shRNA screening and provided a robust short list of synthetic lethal master regulators." (PMID 29880876, 2018). "This neuroblastoma cell line constitutively expresses high levels of MYCN which can be repressed by the addition of tetracycline." (PMID 29954071, 2018). "For neuroblastoma, tumor stage, MYCN oncogene amplification and age are known prognostics factors, but not necessarily so for HR patients." (PMID 30012197, 2018). "The cooperative effect of MYCN amplification and ALKF1174L mutation seems to be sufficient to drive malignant transformation in neuronal progenitor cells towards neuroblastoma tumors." (PMID 29492199, 2018). "MYCNOS-01, MYCNOS-02 and MYCN expression levels were assessed in alveolar rhabdomyosarcoma and neuroblastoma cell lines and tumor samples from patients using Affymetrix microarray data and quantitative RT-PCR." (PMID 29466962, 2018). "In example, MYCN-driven neuroblastoma consistently showed a notable sensitivity to CHK1 and/or PARP inhibitors, in vitro and in xenograft models." (PMID 30166519, 2018). "Amplification of MYCN, a gene belonging to the Myc family of transcription factors, is found in around 50% of advanced stage neuroblastoma patients and is a significant marker of poor prognosis." (PMID 29954071, 2018). "Particularly, the transcription of MYCN was comparable in tumor and DTC samples, as well as the transcription of MYC, which was earlier shown to be anti‐correlated with MYCN in neuroblastoma." (PMID 28921546, 2018). "MYCN is amplified in small cell lung cancers and several pediatric tumors, including alveolar rhabdomyosarcomas and neuroblastomas." (PMID 29466962, 2018). "The expression of KDM4B was highly correlated with that of the MYCN oncogene in neuroblastoma, and it formed a complex with N-Myc protein, thereby facilitating its function by maintaining low levels of repressive H3K9me2/me3 marks at Myc-binding sites." (PMID 29342868, 2018). "Deregulated persistent expression of MYCN plays critical role in neuroblastoma pathogenesis and is a well-defined driver of tumor initiation from early neural crest precursors." (PMID 29755654, 2018). "The analysis of gene expression array data of 102 neuroblastomas (Stage 4 and non-MYCN amplified) showed that there is a trend toward the association between high BAP1 and Bax expression and better relapse-free survival of the patients." (PMID 29686263, 2018). "PI3K inhibition in MYCN-driven murine neuroblastoma leads to decreased levels of MYCN protein and tumor regression." (PMID 30326621, 2018). "Neuroblastomas with a high mitosis-karyorrhexis index (High-MKI) are often associated with MYCN amplification, MYCN protein overexpression and adverse clinical outcome." (PMID 29464082, 2018).
neuroblastoma (continued). "Our latest study further showed that MYCN protein overexpression was detected in ∼20% of patients with neuroblastoma of undifferentiated (NB-U) and poorly differentiated (NB-PD) subtypes." (PMID 29464082, 2018). "SHEP-21 N is a MYCN single copy neuroblastoma cell line that expresses high levels of a MYCN transgene." (PMID 29880876, 2018). "For instance, amplification of MYCN is observed in approximately 20% of neuroblastoma cases and associated with poor prognosis, and ALK mutation is identified in nearly 1% of neuroblastoma cases." (PMID 30362960, 2018). "To identify genes that are regulated by TFAP4 in MYCN-amplified neuroblastoma, we profiled genome-wide transcriptional changes by RNAseq 40 h after shRNA against TFAP4 was induced." (PMID 29880876, 2018). "Our current understanding of the oncogenic role of LIN28B in neuroblastoma tumor formation is that it is a negative regulator of the let-7 family of miRNAs that directly target MYCN." (PMID 29492199, 2018). "The predictive power is better than some existing prognostic factors in neuroblastoma, such as age, tumor stage, MYCN oncogene amplification and TERT expression." (PMID 30012197, 2018). "Approximately 20% of patients with neuroblastoma encounter MYCN amplification, which is a predictor of poor prognosis." (PMID 30581774, 2018). "An alternative approach to treating MYCN-amplified neuroblastoma patients would be to target proteins whose essentiality is only manifested in MYCN-amplified tumors (MYCNAmp synthetic lethal)." (PMID 29880876, 2018). "An alternative transcript of MYCNOS, MYCNOS-01, post-transcriptionally regulates MYCN levels and affects growth in MYCN-amplified rhabdomyosarcoma and neuroblastoma cells." (PMID 29466962, 2018). "Several gene mutations, deletions or chromosomal rearrangements are involved in the onset of neuroblastoma and are associated with poor outcome, such as ALK, PHOX2B and MYCN gene amplification." (PMID 29930753, 2018). "Mechanistically, we observed that in MYCN-amplified neuroblastoma cells, silencing of TFAP4 induces neurite outgrowth and upregulation of the neuronal marker GAP43." (PMID 29880876, 2018). "MYCN amplification was determined to be a strong prognostic factor for survival in neuroblastoma in the late 1980s, and today remains one of the most important validated biomarkers." (PMID 30326621, 2018). "Of note is that loss of chromosome 1p is frequently reported to co-occur with MYCN amplification in human neuroblastoma." (PMID 29492199, 2018). "The following agents continue to be studied in children with neuroblastoma due to their role in regulating MYCN." (PMID 30326621, 2018). "Silencing TFAP4 selectively inhibits MYCN-amplified neuroblastoma cell growth both in vitro and in vivo, in xenograft mouse models." (PMID 29880876, 2018). "MYCN protein is known to play a key oncogenic role in both alveolar rhabdomyosarcomas and neuroblastomas." (PMID 29466962, 2018). "Accordingly, our study showed that CX-5461 down-regulated MYC and MYCN proteins and suppressed growth of neuroblastoma cells." (PMID 29464082, 2018). "Remarkably, the expression of all top 50 correlated genes from the ESC mRNA signature, including FOXM1, increases upon Th-MYCN driven neuroblastoma development." (PMID 30504901, 2018). "The PI3K/AKT/mTOR pathway appears to play a role in MYCN stabilization and aberrant activation of the pathway has been demonstrated in neuroblastoma." (PMID 30326621, 2018). "Several mouse models have been developed to study neuroblastoma development in vivo as a consequence of MYCN or ALK overexpression in neural crest cell progenitors." (PMID 29498681, 2018).
neuroblastoma (continued). "As a rule, c-kit- and/or SCF-positive cases were undifferentiated or slightly differentiated neuroblastomas at a late stage (III and IV) and with unfavorable molecular characteristics, such as MYCN amplification and 1p36 allelic loss." (PMID 30116755, 2018). "Suppressor miR-34a targets MYCN and inhibits neuroblastoma cell proliferation in vitro and in vivo in mice." (PMID 30237861, 2018). "As a proof of principle, differentiation upon ATRA treatment of two MYCN-amplified neuroblastoma cell lines, IMR32 and BE2C, was measured both in cell cultures and in tumours formed on the chick chorioallantoic membrane (CAM)." (PMID 29301505, 2018). "MYCN is an oncogene and it is considered amplified when more than four copies are present in the tumor; this is found in approximately 20% of neuroblastomas." (PMID 30154341, 2018). "MYCN-amplified neuroblastoma cells have a targeted benefit as HCI-2509 downregulates the MYCN upregulated gene set." (PMID 29515779, 2018). "SMC2 expression is elevated in MYCN-amplified human neuroblastoma cells and down regulation of SMC2 induced DNA damage and apoptosis in human neuroblastoma cells." (PMID 29467813, 2018). "We have previously shown that downregulation of MYCN induces a G1 cell cycle arrest in MYCN-amplified neuroblastoma cell lines." (PMID 29719597, 2018). "They first examined the impact of MYCN amplification on signaling pathways in neuroblastoma and it was comforting to see that the algorithm was able to identify well defined, reasonable signaling pathways affected by the MYCN amplification." (PMID 30134948, 2018). "A recent CRISPR-Cas9 screening of MYCN-amplified neuroblastoma discovered preferential dependency on EZH2." (PMID 30326621, 2018). "In conclusion, this report is the first to identify miR-665 as a potent tumor suppressor that directly targets the 3’-UTRs of HDAC8, c-MYC, and MYCN, each of which is involved in neuroblastoma tumorigenesis." (PMID 30237861, 2018). "As well as MYCN amplification (MNA), high risk neuroblastomas have also been shown to elevate telomerase reverse transcriptase (TERT) expression through deregulatory genomic rearrangements." (PMID 29505958, 2018). "The DLL1 ligand was observed to be the most expressed Notch pathway component in MYCN amplified neuroblastoma cells and its downregulation, with miRNAs, induced differentiation and an arrest of cell proliferation." (PMID 28525978, 2017). "MYCN-amplification and -overexpression is considered the most robust prognostic factor for neuroblastoma patients, indicating poor outcome, even in localized disease, and it is used as a biomarker for patient stratification." (PMID 28358317, 2017). "By inhibiting TWIST expression, the apoptotic response of MYCN-amplified neuroblastoma can be restored, providing evidence of a therapeutic target for drug development." (PMID 28358317, 2017). "The transgenic Th‐ALKF1174L/MYCN model develops spontaneous abdominal neuroblastomas in an immunocompetent background." (PMID 28432815, 2017). "Afterwards, numerous studies have revealed several genetics abnormalities in Neuroblastoma such as MYCN gene amplification, numerical chromosome abnormalities and non-random chromosome gains and losses." (PMID 28056863, 2017). "Genes whose promoters contain E-box motifs and whose expression changed in MYCN-3 cells (neuroblastoma) upon induction of MYCN [GeneID=4613]." (PMID 28423528, 2017). "It was interesting to find that CDDO as a single agent and in combination with ATRA induced differentiation of MYCN amplified IMR32 cells which to our knowledge is a first report demonstrating the ability of CDDO to induce neuroblastoma differentiation." (PMID 29018329, 2017). "High-risk neuroblastoma (NB) with MYCN amplification is a highly metastatic tumor in children." (PMID 27894074, 2017). "We propose that in the future the selective inhibitors of PI3K can be used to supplement the current therapies for the MYCN-amplified neuroblastomas." (PMID 29137381, 2017).
neuroblastoma (continued). "Clinical stage, age, histopathology, MYCN copy number status, 11q LOH, and DNA ploidy are important for risk assessment in patients with neuroblastoma." (PMID 29296183, 2017). "Genomic analyses for pediatric neuroblastoma have identified recurrent somatic mutations in cancer-related genes such as ALK, PTPN11, ATRX, MYCN, and NRAS." (PMID 28521285, 2017). "Given the central role of MYCN in neuroblastoma biology, understanding its upstream regulators is also important." (PMID 28055978, 2017). "We showed that the synergy occurs in TRKA overexpressing as well as in MYCN overexpressing and amplified neuroblastoma cells." (PMID 28596528, 2017). "To validate this pathway, we collected 41 unrelated primary neuroblastoma clinical samples with known status of MYCN amplification and profiled gene expression using an alternative customized microarray platform (CustomArray, USA)." (PMID 29137381, 2017). "MYCN copy numbers ranging from 73.5 to 267.0 were detected using ddPCR of tumor gDNA from patients 6–10, who were diagnosed with MYCN-amplified neuroblastomas according to FISH." (PMID 29156716, 2017). "MYCN-amplification was found to be correlated to sensitivity to the BET-inhibitor JQ1 in neuroblastoma cells, leading to impaired growth, increased apoptosis and downregulation of MYCN transcriptional program." (PMID 28358317, 2017). "MondoA, a member of the MYC transcriptional network involved in metabolic control, interacts with MYCN to promote neuroblastoma cell survival through the upregulation of metabolic pathways." (PMID 28358317, 2017). "MYCN down-regulation by CDDO resulted in re-expression of NDRG1 which is otherwise known to be repressed in neuroblastoma." (PMID 29018329, 2017). "A review of the literature indicates that assessment of MYCN status using quantitative real-time PCR and serum/plasma-derived cfDNA presents a promising method to analyze neuroblastoma patient samples." (PMID 29156716, 2017). "Several elegant studies in transgenic zebrafish and mouse models have already demonstrated synergistic effect of expressing activated ALK together with MYCN on inducing neuroblastoma." (PMID 28425916, 2017). "By contrast, neuroblastomas diagnosed later than 18 months or those with amplification of the MYCN oncogene have much worse prognosis." (PMID 28187790, 2017). "Here, we introduce SK-N-ASrOXALI4000, a sub-line of the non-MYCN-amplified neuroblastoma cell line SK-N-AS with acquired resistance to oxaliplatin." (PMID 28192521, 2017). "SF1126 inhibits BRD4 bromodomain binding to acetylated lysine residues with histone H3 as well as PI3K activity in the MYCN amplified neuroblastoma cell line IMR-32." (PMID 28881723, 2017). "The German NB2004 trial protocol for FISH analysis of primary neuroblastoma samples designates MYCN amplification as the detection of > 8 MYCN copies, gain as detection of 3 to 8 copies and ‘single-copy’ as 2 copies." (PMID 29156716, 2017). "The MYCN proto-oncogene plays an important role in neuroblastoma development; about 30%-40% of advanced stage tumors exhibit MYCN amplification, which has been correlated to rapid tumor progression, drug resistance and poor outcome." (PMID 28525978, 2017). "In TH-MYCN mice, MYCN overexpression drives initiation and progression of spontaneous neuroblastoma-like tumors with high penetrance in the sympathetic ganglia." (PMID 28358317, 2017). "Myelocytomatosis oncogene (MYC) family members, including cellular MYC (c-Myc), neuroblastoma derived MYC (MYCN), and lung carcinoma derived MYC (MYCL), have all been implicated as key oncogenic drivers in a broad range of human cancers." (PMID 28245597, 2017). "For controls, we tested HCT116 cells that predominantly expressed MYC and Kelly neuroblastoma cells that expressed MYCN." (PMID 29028833, 2017).
neuroblastoma (continued). "We compared the mRNA expression data obtained for the neuroblastoma samples with known status of MYCN amplification in the three different studies, using the three alternative microarray platforms." (PMID 29137381, 2017). "Here, we introduce a novel model of acquired oxaliplatin resistance, a sub-line of the non-MYCN-amplified neuroblastoma cell line SK-N-AS that was adapted to growth in the presence of 4000 ng/mL oxaliplatin (SK-N-ASrOXALI4000)." (PMID 28192521, 2017). "When normalized on the normal tissues (i-ii), the expression features of the MYCN amplification pathway nodes were usually regulated in the same direction in both the MYCN-amplified and wild-type neuroblastomas." (PMID 29137381, 2017). "Intergenic human snoRNA promoters are enriched in E-boxes which are binding sites for MYC, and in MYCN amplified neuroblastomas, expression of several snoRNAs was reported to be higher compared to non-amplified neuroblastomas." (PMID 29287594, 2017). "Wang and colleagues identified only 3 neuroblastomas harboring ALK amplifications, all also harboring MYCN amplifications, in a cohort of 188 primary neuroblastomas from a patient cohort treated at the Beijing Children’s Hospital." (PMID 29156716, 2017). "It has been shown that MYCN upregulates the expression of several ABC transporters in neuroblastoma." (PMID 28358317, 2017). "Intriguingly, we have identified destabilization of MYC signaling as an early and consistent feature of ML327 treatment that is observed in both MYCN-amplified and MYCN-single copy neuroblastoma cell lines." (PMID 29207623, 2017). "It occurs almost exclusively with MYCN amplification, and has been detected in 7–15% of MYCN-amplified neuroblastomas." (PMID 29156716, 2017). "MYCN transcription factor is frequently up-regulated in a variety of human cancers, including neuroblastoma." (PMID 28881723, 2017). "Gorlick and colleagues treated a panel of predominantly MYCN-amplified neuroblastoma cell lines grown as xenograft tumors in CB17SC scid−/− mice with the PLK1 inhibitor, volasertib." (PMID 28036269, 2017). "MAPK (MEK) has also previously been linked to MYCN-independent NF1-mediated RA resistance, and MEK inhibition combined with RA treatment was proposed as a potential strategy to treat NF1-deficient neuroblastomas." (PMID 28187790, 2017). "The aim of this work was to assess and compare the cytotoxicity of 2 SSRI, citalopram and escitalopram, on neuroblastoma cell lines including 2 non-MYCN amplified cell lines (rat B104 and human SH-SY5Y) and 2 human MYCN amplified cell lines (IMR32 and Kelly)." (PMID 28467792, 2017). "Here we show that HDAC11 depletion in MYCN-amplified neuroblastoma cells triggers programmed cell death preceded by an accumulation of mitotic cells characterized by aberrant spindle assembly formation." (PMID 28252645, 2017). "We next assessed ddPCR sensitivity in detecting MYCN amplification in a mixture of genomic DNA isolated from two neuroblastoma cell lines." (PMID 29156716, 2017). "We show here that HDAC11 depletion in MYCN-driven neuroblastoma cell lines strongly induces cell death, mostly mediated by apoptotic programs." (PMID 28252645, 2017). "Depletion of eEF2K (by siRNA) impairs MYCN-amplified neuroblastoma xenograft growth under conditions of caloric restriction." (PMID 29186827, 2017). "MYCN amplification occurs in over 20% of neuroblastoma and contributes to metastasis and chemoresistance." (PMID 28187790, 2017). "The differentiation was accompanied by a decrease in the expression of MYCN whose amplification is known to contribute to the pathogenesis of neuroblastoma." (PMID 29018329, 2017). "We next investigated effect of SF1126 on MYCN amplified neuroblastoma cell lines IMR-32 and CHLA-136." (PMID 28881723, 2017). "Similar to MYCN, ALK amplification, and gain of function mutations are often correlated with poor outcome for neuroblastomas." (PMID 29018329, 2017).